TGFBR2 (transforming growth factor beta receptor 2)
Diseases named in the same sentence as TGFBR2 in open-access papers (continued):
Sharing a sentence is not in itself a finding about the gene and the disease.
breast tumor (12 papers, 2008 to 2025). "The result implicated that the breast tumour cells had developed abilities to reduce their responsiveness to TGFβ by down-regulating TGFBR2 expression." (PMID 26703884, 2015). "Significantly higher TGFB1 and TGFB3 mRNA levels and lower TGFBR2 mRNA levels were observed in the primary breast tumours compared with their matched normal tissues." (PMID 26703884, 2015). "The TGFBR2 mRNA levels were reduced by around two-thirds in breast tumours compared with matched normal tissues, which was consistent with a study evaluating the protein levels of TβRII." (PMID 26703884, 2015). "MCP-1 and IL6 decreased and VEGF level increased in all types of breast tumors with low TGFBR2 expression." (PMID 25280532, 2014). "Moreover, we were able to show an increase of TGFBR1 and TGFBR2 mRNA expression in breast tumors from Elovl5−/− mice compared to tumors from Elovl5+/+." (PMID 36056008, 2022). "ACVR1C, TGFBR2, TGFBR3, ACVR2A, ACVR1, BMPR1A and BMPR2 were lower in breast tumours while ACVR1B and BMPR1B exhibited relatively higher expression levels in paired tumours compared with normal breast tissues, in the TCGA_BRCA cohort." (PMID 37333824, 2023). "Three commonly predicted targets of the miR-17/92 cluster showing anti-correlated expression are tumor suppressors TGFBR2, DCN, and CAV1 which were under-expressed in the breast tumor tissues." (PMID 27213017, 2016). "Here, we detected higher TGFBR2 expression in triple‐negative tumors compared to luminal‐like tumors as well as in ER‐negative compared to ER‐positive breast tumor tissue." (PMID 30004628, 2018). "Our three markers are not included in major commercial gene expression marker sets that predict breast tumor recurrence such as MammaPrint (70 markers) or Oncotype DX (16 markers), although TGF β receptor II (TGFBR2) was among the initial set of 250 candidate genes considered by Oncotype DX." (PMID 21651811, 2011).
cervical carcinoma (12 papers, 2017 to 2023). A carcinoma arising from either the exocervical squamous epithelium or the endocervical glandular epithelium. "TGFBR2 has been reported to regulate the Hedgehog pathway and cervical cancer cell proliferation and migration by mediating SMAD4." (PMID 35241117, 2022). "An analysis of 178 cervical carcinomas by The Cancer Genome Atlas (TCGA) network found recurrent deletions of TGF-beta receptor 2 (TGFBR2, 3p24.1) and SMAD4 (18q21.2) in 36% and 28% of analyzed samples, respectively." (PMID 32188026, 2020). "Both TGFBR2 and hTERT had predictive values in cervical cancer, with the maximum area under the curve (AUC) reaching 0.630 and 0.652 for TGFBR2 and hTERT abundance, respectively (red arrows)." (PMID 28195144, 2017). "In this study, we investigated the correlation of hTERT expression with survival and examined the possible role of TGFBR2 in the diagnosis and prognosis of cervical cancer." (PMID 28195144, 2017). "When we focused on TGFBR2 expression in the prognosis of cervical cancer, our results showed that TGFBR2 expression was correlated with FIGO stage, differentiation grade, pelvic lymph node metastasis, and recurrence." (PMID 28195144, 2017). "In view of the process of tumorigenesis is complex and the patients’ samples shows little uniformity, our further study aimed to verify the correlation of TGFBR2 and hTERT in cervical cancer cells." (PMID 28195144, 2017). "It was identified that pelvic lymph node metastasis and TGFBR2 expression were independent prognostic factors in cervical cancer." (PMID 28195144, 2017). "One recent study of 228 cervical cancers using TCGA data identified SHKBP1, ERBB3, CASP8, HLA-A, and TGFBR2 as novel significantly mutated genes, and previously identified pathogenic genes including PIK3CA, EP300, ARID1A, and NFE2L2 were also confirmed." (PMID 28390392, 2017). "One of the largest cervical cancer sequencing efforts—The Cancer Genome Atlas (TCGA) Project—reveals novel mutations in several genes, including SHKBP1, ERBB3, CASP8, HLA-A and TGFBR2, amplifications in immune targets PD-L1 and PD-L2, by sequencing 228 primary cervical cancer patients." (PMID 35205332, 2022). "Cai and colleagues could demonstrate mir-17 induction in cervical cancer leading to induced cell proliferation and migration by targeting TGFBR2." (PMID 30001402, 2018). "Patterns of dual TGFBR2/hTERT protein expression in the 164 cases of cervical cancer included: TGFBR2high/hTERThigh in 17 (10.4%) cases, TGFBR2high/hTERTlow in 68 (41.5%) cases, TGFBR2low/hTERThigh in 24 (14.6%) cases, and TGFBR2low/hTERTlow in 55 (33.5%) cases." (PMID 28195144, 2017). "The TGFBR2 expression was low or undetectable in most cervical cancer tissues." (PMID 28195144, 2017). "Similarly with other tumors, our study revealed that TGFBR2 was underexpressed in cervical cancer tissue, but highly expressed in chronic cervicitis." (PMID 28195144, 2017). "However, few studies have been focused on the role of TGFBR2 in the diagnosis and prognosis of cervical cancer." (PMID 28195144, 2017). "Our results suggest a possibility that simultaneous application of TGFBR2 agonist and hTERT inhibitors may be developed as a therapeutic strategy for treating cervical cancer, especially in the patients with TGFBR2low/hTERThigh expressions." (PMID 28195144, 2017). "We also tested whether the dual TGFBR2/hTERT tumor genotype is a more reliable predictor for the prognosis of cervical cancer than TGFBR2 or hTERT alone." (PMID 28195144, 2017). "Using ToppCluster to generate a network of genes shared between Tgfbr2 deficient CD34+ anorectal transitional SCC cells and published datasets of aggressive human cancers we found that a number of genes were commonly overexpressed in human cancers including cervical carcinoma." (PMID 28219480, 2017). "Thus, TGFBR2 is a cancer suppressor and a potential therapeutic target in cervical cancer." (PMID 28195144, 2017).
cervical carcinoma (continued). "Thus, using the altered expression of TGFBR2 and hTERT to predict the prognostic of cervical cancer may have clinical significance." (PMID 28195144, 2017). "However, the relevance of survival to the expression of TGFBR2, hTERT or TGFBR2/hTERT has not been previously investigated in cervical cancer tissues." (PMID 28195144, 2017). "Low expression of TGFBR2 (but not hTERT) seems to be related to poor prognosis for cervical cancer patients, while the concomitant low expression of TGFBR2 and high expression of hTERT, may be considered as a better survival biomarker than low expression of TGFBR2 alone." (PMID 28195144, 2017).
thoracic aortic aneurysm (12 papers, 2010 to 2026). An aneurysm formed in the wall of the proximal portion of the descending aorta proceeding from the arch of the aorta. "Background/Objectives: Thoracic aortic aneurysms have long been associated with germline mutations such as FBN1, TGFBR2, and COL3A1, which predispose to Marfan, Loeys-Dietz, and Ehlers-Danlos syndromes, respectively." (PMID 42074482, 2026). "Previous data from literature indicated the contribution of TGFBR1 and TGFBR2 genes in thoracic aortic aneurysms and dissections." (PMID 30255099, 2018). "It is also known that BAV is more frequent in patients with thoracic aortic aneurysm (TAA) related to mutations in ACTA2, FBN1, and TGFBR2 genes." (PMID 28883797, 2017). "Indeed, pathogenic variants or deficiency of TGF-β pathway genes, including TGFB2, TGFB3, TGFBR1, TGFBR2, and SMAD3, confer risks for aortic destruction and thoracic aortic aneurysm formation." (PMID 38916960, 2024).
ovarian carcinoma (11 papers, 2012 to 2024). A malignant neoplasm originating from the surface ovarian epithelium. "On the other hand, we found an increase in TGFBR2 protein levels in ovarian cancer tissue, but not in the A2780 cell line." (PMID 26091707, 2016). "TGFB1 and TGFBR1 expression did not affect survival (data not shown), while TGFB2, TGFB3, TGFBR2, and TGBR3 overexpression decreased patient survival among ovarian cancer patients when the microarray data was assessed." (PMID 38196068, 2024).
renal fibrosis (11 papers, 2013 to 2025). A final common manifestation of a wide variety of chronic kidney diseases characterized by glomerulosclerosis and tubulointerstitial fibrosis. "Given prior reports linking Tgfbr2 deletion to enhanced MF recruitment, the Rtn3-null induced loss of the Tgfb2-Tgfbr1/2 axis suggests potential hyper-activation of MFs, resulting in renal fibrosis." (PMID 38937317, 2024). "This binding inhibits the ubiquitin‐proteasome‐mediated degradation of TGFBR2 and increases TGFβ1 levels, thereby enhancing the profibrotic effects of the TGFβ1 signaling pathway and promoting the progression of renal fibrosis and DKD." (PMID 40799164, 2025). "The augmented TGFBR2 and TGFβ1 levels in diabetic kidneys potentiate the TGFβ1 signaling pathway, thereby facilitating renal fibrosis development." (PMID 40799164, 2025). "In this study, we found that Gal3 binds to TGFBR2, potentiating the effect of TGFβ1 and promoting renal fibrosis, consistent with reports of Gal3‐induced fibrosis in other organs." (PMID 40799164, 2025). "In contrast with our expectations, we found that the miR−122−5p mimic enhanced renal fibrosis with the upregulation of TGFBR2." (PMID 36499744, 2022). "To confirm whether Gal3 promotes renal fibrosis mainly through the regulation of the TGFβ1 signaling pathway, we treated renal fibroblasts with Gal3 and TGFβ1, along with either the TGFBR2 inhibitor (LY2109761) or the TGFβ1 signaling pathway inhibitor (PD169316)." (PMID 40799164, 2025). "The study findings suggested that TGFBR2 (a pro-fibrotic factor) might be involved in the mechanism by which the miR−122−5p mimic promotes renal fibrosis and FOXO3 (an anti-fibrotic factor) might be involved in the mechanism by which the miR−122−5p inhibitor suppresses renal fibrosis." (PMID 36499744, 2022).
adenoma (10 papers, 2008 to 2025). A neoplasm arising from the epithelium. "For example, mutations in BAX2 and TGFBR2 occur early and are found in over half of LS adenomas; further, mutations continue to accumulate during the progression to high-grade adenomas." (PMID 41463230, 2025). "Consistent with this, ACVR2A is regarded as a driver gene in MSI colorectal adenomas and is—after TGFBR2—the gene with the second highest rate of frameshift variants in MSI adenomas." (PMID 34843512, 2021). "In adenomas with foci of invasive adenocarcinoma, it was noted that the TGFBR2 had mutated in 75% of cases." (PMID 19424478, 2008). "One of the mechanisms hypothesised to cause progression from adenoma to carcinoma is mutation of mononucleotide repeats in the coding region for the TGF- β type II receptor (TGFBR2)." (PMID 19424478, 2008). "Interestingly, over half of LS adenomas possess TGFBR2 gene mutations." (PMID 41463230, 2025). "A previously established CRC mouse model of Tgfbr2 conditional knockout revealed that Tgfbr2 inactivation promoted the progression of adenomas initiated by Apc inactivation to invasive adenocarcinomas with a mucinous component." (PMID 27835699, 2016). "Such analyses identified three genes (ACVR2A, TGFBR2, and SLC22A9) and an additional two genes (TCERG1 and TRIM59) whose mutations were enriched for clonal and adenoma-specific categories, respectively." (PMID 26336987, 2015). "Because the inactivation of TGFBR2 is coordinated with the transition from adenoma to carcinoma, the progressive inactivation of TGFBR2 in cancer-adjacent and tumor tissues is expected." (PMID 22905095, 2012). "TGFBR2 mutation appears to be a late event in MSI adenomas and tightly correlated with progression of these adenomas to malignant carcinomas." (PMID 18941508, 2008).
bladder cancer (10 papers, 2014 to 2022). "Notably, TGFBR2 mutations are frequently found in bladder cancer patients." (PMID 31842336, 2019). "miR-520f, which is capable of reversing EMT in bladder cancer cells, downregulates expression of TGFBR2." (PMID 31842336, 2019). "Deletion of Tgfbr2 decreased the population of cancer stem cells, attenuated proliferation, and induced apoptosis of bladder cancer cells in vivo." (PMID 31842336, 2019). "There, a loss of TGF-β1 receptors, TGFBR1 and TGFBR2, correlated with the invasive tumor stage, high grade, and lymphovascular invasion while enhanced TGF-β1 levels in bladder cancer tissues and plasma of patients were associated with tumor invasiveness." (PMID 31842336, 2019). "To determine the function of TGF-β signaling in bladder cancer progression, we conditionally knocked out the Tgfbr2 in mouse model after a N-butyl-N-4-hydroxybutyl Nitrosamine induced bladder carcinogenesis." (PMID 27378170, 2016). "In this study, TGFBR2 was demonstrated to be downregulated in bladder cancer tissues." (PMID 35241117, 2022). "Likewise, circFoxo3 is downregulated in bladder cancer tissues and promotes TGFBR2 expression by binding to miR-9-5p, which inhibits the growth and metastasis of bladder cancer cells in the end." (PMID 34445958, 2021). "We showed that depletion of Tgfbr2 reduced the invasiveness of bladder cancer induced by BBN." (PMID 27378170, 2016). "Loss of the IQGAP1 tumor suppressor leads to increased expression of TGFBR2 and activated the TGF-β1 signaling pathway, thereby stimulating growth of human bladder cancer cells." (PMID 31842336, 2019). "For bladder cancer, we selected TGFBR1 and for breast TGFBR2 due to their tissue-specific expression profiles." (PMID 28775339, 2017).
esophageal squamous cell carcinoma (10 papers, 2013 to 2025). Esophageal squamous cell carcinoma (ESCC) is a type of esophageal carcinoma (EC) that can affect any part of the esophagus, but is usually located in the upper or middle third. "Alteration in TGFBR2 have been associated to the Lynch syndrome, squamous cell carcinoma of the esophagus and the connectivopathies Loeys-Dietz and type-2 Marfan syndromes." (PMID 33821390, 2021). "Beyond its role in EndMT, GDF15 promotes AKT phosphorylation in a TGFBR2-dependent manner, hence increasing the resistance of esophageal squamous cell carcinoma cells to low-dose cisplatin." (PMID 41502509, 2025). "Furthermore, GDF15 promoted the progression of Esophageal Squamous Cell Carcinoma through the activation of TGFBR2." (PMID 36698183, 2023).
Aortic dissection (9 papers, 2016 to 2025). Aortic dissection refers to a tear in the intimal layer of the aorta causing a separation between the intima and the medial layers of the aorta. "These genes were then associated with the phenotype of “aortic dissection; artery aneurysm” by Phenolyzer, and the result revealed one heterozygous T-to-C transition c.1613T > C in TGFBR2, which leads to a substitution of valine to alanine at codon 538 (p.Val538Ala) in the TGFBR2 kinase domain." (PMID 32528524, 2020).
Autoimmunity (9 papers, 2009 to 2023). The occurrence of an immune reaction against the organism's own cells or tissues. "Furthermore, in neonate physiological lymphopenia, induction of loss of homeostatic control by deletion of the Tgfbr2 gene at an early stage results in the onset of autoimmunity and death before five weeks of age." (PMID 33923792, 2021). "Studies using targeted disruption of Tgfbr2 in helper T cells to induce autoimmunity are consistent with the idea that TGFβ affects autoimmunity by modulating interactions between DCs and T cells." (PMID 19625278, 2009). "Furthermore, transgenic mouse model with Tgfbr2 conditional knock-out in dendritic cells develop multiorgan autoimmunity and premature thymus involution." (PMID 24804794, 2014). "Unlike deleting floxed Tgfbr2 alleles in developing thymocytes using a Cd4-Cre transgene, deleting floxed Tgfbr2 alleles in mature T cells in the periphery using a distal-Lck-Cre transgene does not lead to autoimmunity or lymphoproliferation under steady state." (PMID 37217798, 2023). "As SLE is an autoimmune disorder of the connective tissue, the other top GSEA term is ‘chondrocyte development’, represented by the genes CHST11, COL11A, EXT1, and TGFBR2." (PMID 37048133, 2023). "However, if deletion of the Tgfbr2 gene is controlled to occur at a later stage, then there will be no development of autoimmunity in neonate mice even in the presence of lymphopenia." (PMID 33923792, 2021).
migraine (9 papers, 2014 to 2025). "Of the TGFBR2 variants, p.Met148Leu was exclusive to the hemiplegic migraine cohort." (PMID 40869943, 2025). "Given the established association between migraine and vascular instability and inflammation, the pathogenic variants in TGFBR2 may contribute to vascular dysfunction, potentially increasing susceptibility to migraine." (PMID 40869943, 2025). "Of note, hsa-miR-605-3p targets COL4A1, PNKD, TGFBR2, and YAP1, which have been identified as susceptible genes in migraine patients." (PMID 36704329, 2022). "In this context, it is noted that polymorphisms in genes including TGFBR2, TSPAN2, and PRDM16 are also associated with migraine risk, underlining a potentially important role of these genes in migraine pathogenesis and therapy success in migraine." (PMID 35222013, 2021). "A similar pattern was observed for rs6791480 (near TGFBR2) and migraine characterized by inhibited daily activity due to pain (pcor = 0.013) among fully qualifying migraineurs but null in the augmented samples." (PMID 33643179, 2020). "Furthermore, genetic variants related to MMP16, TGFBR2, TSPAN2, and LMP1 have been linked to therapy outcome changes with sartans in migraine." (PMID 35222013, 2021). "Although these variants are rare, occurring in single patients, the role of TGFBR2 in the TGF-beta signalling pathway, which regulates vascular integrity and inflammation, suggests they may contribute to vascular instability in these migraine patients." (PMID 40869943, 2025).
Obesity (9 papers, 2006 to 2026). Accumulation of substantial excess body fat. "Mir-21, here significantly associated with obesity phenotypes, has been reported to be involved in regulation of adipogenesis and lipid metabolism through its gene targets TGFBR2 and PPARalpha respectively." (PMID 22589741, 2012). "This in fact was the case for each of the three genes (Tgfbr2, C3ar1 and Zfp90) we recently reported as being causal for obesity in the BXD cross." (PMID 16886998, 2006). "In mice, by CIT analysis and validation studies using genetically engineered animals, Zfp90 (zinc finger protein 90), C3ar1 (complement component 3a receptor 1) and Tgfbr2 (transforming growth factor, beta receptor II) have been identified as new QTGs involved in susceptibility to obesity." (PMID 29186889, 2017).